SDC1 (syndecan 1)
Diseases named in the same sentence as SDC1 in open-access papers (continued):
Sharing a sentence is not in itself a finding about the gene and the disease.
tumor (continued). "CSF-1, CSF-1R, and IL-34 were weakly negatively associated with tumor purity, while the lack of association between immune cell infiltration and gene expression of PTPRZ1 and syndecan-1 was also reflected by tumor purity values." (PMID 29796177, 2018). "Through this co-operation, heparanase and syndecan-1 control tumor cell growth, adhesion, spread, and signaling at a distance through exosomes." (PMID 30413079, 2018). "Since stromal Sdc1 has previously been shown to stimulate angiogenesis, we studied the tumor vasculature by labeling primary tumor sections with an antibody to the endothelial cell marker CD31." (PMID 29976229, 2018). "This study showed that the Sdc1 was expressed in the tumor epithelium in the vast majority or 90% of the primary IDC, and most frequently, it was a strong expression (56.7%)." (PMID 30151336, 2018). "The role of syndecan-1 in cancer cell migration and tumor growth has been described in the previous section." (PMID 30135409, 2018). "It was reported that the cell surface proteoglycan syndecan 1 was up-regulated in the malignant breast stromal fibroblasts, creating a favorable milieu for tumor cell growth." (PMID 27901488, 2017). "Of note, the cell surface HS proteoglycan syndecan-1 coupled ternary receptor complex (prevalent on tumor cells and activated endothelial cells) has been described, whereby syndecan-1 clusters IGF-1R and integrins, leading to integrin activation." (PMID 28038446, 2017). "The cell-surface heparan sulfate proteoglycan syndecan-1 is important for tumor cell proliferation, migration, and cell cycle regulation in a broad spectrum of malignancies." (PMID 29216821, 2017). "Syndecan-1 is critically involved in tumor cell proliferation and migration in a wide range of malignancies." (PMID 29216821, 2017). "This study emphasizes the importance of the localization of syndecan-1 when considering its effects on tumor cell fate." (PMID 29216821, 2017). "Syndecan-1 (SDC1) is an important member of syndecan family, which expression has been associated with prognosis and treatment response in a various tumor types, including solid tumors and hematolymphoid malignancies." (PMID 29340066, 2017). "In agreement with previous reports, decreased Sdc1 levels were detected by immunostaining in the tumor, as compared to normal colonic tissue samples derived from wt mice." (PMID 28350804, 2017). "EGFR plays an essential role in IBC progression and is correlated with Syndecan-1 expression in some tumor entities." (PMID 28270211, 2017). "There is some documentation about the expression of syndecan-1 in OSCC, seems to be associated with the differentiation status of the tumor cells." (PMID 26849680, 2016). "Subsequently, we focused on the expression of SDC1 in fibroblasts, as its induction in the breast stroma is considered a promoter of tumor growth and a marker of poor clinical outcome." (PMID 27434331, 2016). "Significantly, a higher S1P level associated with a higher syndecan-1 level in HCC serum, and a higher S1P1 level associated with a lower syndecan-1 level in HCC tumor tissues." (PMID 27556509, 2016). "Higher serum levels and lower tissue levels of syndecan-1 both reflect a high tumor burden and are promising prognostic marker for HCC." (PMID 27556509, 2016). "The cell surface proteoglycan syndecan 1 (SDC1) is overexpressed in the malignant breast stromal fibroblasts, creating a favorable milieu for tumor cell growth." (PMID 27434331, 2016).
tumor (continued). "Similar peptides were designed to block IGF1R binding to syndecan-1/αvβ3 integrin complex and inhibit the integrin activity in endothelial and tumor cells." (PMID 26869927, 2016). "A good example is breast cancer, where high levels of syndecan-1 expression, particularly in the tumour stroma, are an indicator of poor prognosis." (PMID 27408707, 2016). "Under these conditions, an autocrine TGF-β loop is formed leading to SDC1 overexpression, known to facilitate tumor growth and angiogenesis." (PMID 27434331, 2016). "Taken together, our study demonstrates that S1P induces advanced tumor phenotypes of HCC via establishing an MMP-7/syndecan-1/TGF-β1 autocrine loop, and implicates targetable S1P1-PI3K/AKT-HPSE-MMP-7 signaling axe in HCC metastasis." (PMID 27556509, 2016). "Fibroblasts of the tumour stroma that surrounded the neoplastic nests were positive for SDC1 in 34 out of 163 (21%) of the tumours." (PMID 25935541, 2015). "Recent studies show that the shed syndecan-1 also translocates to the nucleus of both tumor cells and bone-marrow-derived stromal cells." (PMID 26420915, 2015). "Intact syndecan-1 contain a nuclear localization sequence RMKKK in the cytoplasmic domain, and this sequence is necessary for translocation of the full-length syndecan-1 to the nucleus in mesenchymal tumour cells." (PMID 26068620, 2015). "At the tissue level, the expression levels of SDC1 and the released extracellular domain of SDC1 correlate with tumor malignancy, phenotype, and metastatic potential for both solid and hematological tumors in a tissue-specific manner." (PMID 26293675, 2015). "As a consequence, membrane-bound and soluble syndecan-1 can have opposite effects on cancer cells and can influence a wide range of behaviors such as tumor growth and metastasis, chemokine localization, leukocyte trafficking, and pathogen virulence." (PMID 26420915, 2015). "The value of circulating levels of SDC1 was not consistently associated with tumor grade or characteristics, but the combination of SDC1 and bFGF/FGF2 in patient serum has a strong association with tumor progression and prognosis in selected cancer types." (PMID 26293675, 2015). "Marker analysis suggested a shift of SDC-1 expression from epithelial tumour cells to myofibroblasts within the connective tissue surrounding the tumour cells." (PMID 25598217, 2015). "In cancer, growing evidence indicates that deregulation of SDC1 contributes to the development and progression of different tumor types." (PMID 26293675, 2015). "In this tumor type stromal syndecan-1 expression is an independent prognostic marker, whereas epithelial syndecan-1 expression predicts better prognosis only in resectable tumors." (PMID 26420915, 2015). "Soluble SDC1 is biologically active and can intensify the binding between growth factors with their receptors in tumor stroma." (PMID 26293675, 2015). "Syndecan-1 (Sdc1), a predominant member of type I transmembrane heparan sulphate proteoglycans, plays important roles in inflammation, wound healing and tumour progression 6–8." (PMID 25702768, 2015). "For example, the expression and shedding of syndecan-1 is upregulated in tumor cells, with the shed portion comprising an intact extracellular domain bearing the extracellular portion of the core protein and heparan sulfate moieties." (PMID 25686828, 2015). "A recent study showed that the proportion of syndecan-1 positive cells correlated with tumor grade better than the amounts demonstrated by immunohistochemistry, nuclear grade, and localization of syndecan-1." (PMID 26420915, 2015). "On the basis of these experiments we developed a synthetic syndecan-1 cCTF peptide inhibitor that suppresses syndecan-1 mediated tumor cell migration." (PMID 26378057, 2015). "In normal prostate tissue syndecan-1 is expressed mainly by epithelial cells while in tumors an overall increase of syndecan-1 expression was observed in the tumor stroma along with its disappearance from tumor epithelial cells." (PMID 26420915, 2015).
tumor (continued). "The efficient adhesion and directional movements of tumor cells migrating on the surface of a fibroblast layer can be explained by the ordered structure of ECM facilitated by the expression of syndecan-1 on the surface of fibroblasts." (PMID 25885552, 2015). "This study demonstrated that Syndecan-1 liposomes were able to release cargo into IGF1-R expressing tumor cells." (PMID 26627455, 2015). "Several studies demonstrate that syndecan-1 expression in cancer is significantly correlated with tumor cell differentiation and prognosis." (PMID 26420915, 2015). "Selective expression of syndecan-1 in tumor-initiating cell lines suggests a role of syndecan-1 for cancer stem-cells." (PMID 26420915, 2015). "When heparanase expression was high in the tumor, soluble SDC1 formed a complex with VEGF, which activated VEGF receptors on adjacent endothelial cells." (PMID 26293675, 2015). "A number of findings suggest that Syndecan-1 is involved in the stimulation of CSC or tumor initiating cells (TIC) and that this can affect disease relapse and resistance to therapy (and refs therein)." (PMID 26460958, 2015). "The growth advantage conferred by syndecan-1 overexpression was accompanied by increased tumor angiogenesis." (PMID 26420915, 2015). "Syndecan-1 is a surface expressed heparan sulphate proteoglycan, which is upregulated by several tumor types and involved in tumor cell migration and metastasis." (PMID 26378057, 2015). "In squamous oral carcinoma stromal syndecan-1 inversely correlates with tumor grade and invasiveness." (PMID 26420915, 2015). "Syndecan-1 also affects other aspects of tumor progression, such as angiogenesis promotion during tumorigenesis." (PMID 26558271, 2015). "Soluble form of syndecan-1 can accumulate survival factors within the microenvironment, representing a sort of sponge for these factors around the tumor cells." (PMID 26425544, 2015). "WNT1 signaling and tumor growth are enhanced by syndecan-1 in mammary gland tumors, and syndecan-1 has a role in the ability of Wnt1 to induce the accumulation of mammary progenitor cells." (PMID 26420915, 2015). "Experimental data also suggest that syndecan-1 coordinates the expression of various proteoglycans in different tumor types, although the effect varies largely from one tissue type to other." (PMID 26420915, 2015). "The basal syndecan-1 level and its cellular localization are however crucial for understanding the sequential changes involving malignant transformation, tumor progression, and advanced or disseminated cancer stages." (PMID 26420915, 2015). "Our data indicate that the syndecan-1 cCTF antagonizes syndecan-1 dependent tumor cell migration in vitro and in vivo by dysregulating proadhesive signaling pathways and suggest that the cCTF can be used as an inhibitory peptide." (PMID 26378057, 2015). "The basal syndecan-1 level is also crucial for understanding the sequential changes involving malignant transformation, tumor progression, and advanced or disseminated cancer stages." (PMID 26420915, 2015). "Syndecan-1 accumulates survival factors within the microenvironment, representing a sort of sponge for these factors around the tumor cells." (PMID 26425544, 2015). "To continue, based on studies in ARH-77 human lymphoblastoid cells, shed SDC-1 is established to promote tumor growth and progression in vivo, mediated by the crosstalk between tumor and host cells." (PMID 24551591, 2014). "Functionally, this correlates well with the proposed role of SDC1 as a coreceptor which activates mitogenic growth factor signaling which in turn modulates tumor angiogenesis, cell adhesion, and motility." (PMID 25140302, 2014). "SDC1 participates in the generation of a proangiogenic microenvironment, supporting tumor growth and metastatic spread." (PMID 25140302, 2014).
tumor (continued). "Therefore, it has been suggested that the loss of SDC-1 gene expression is related to tumor progression and that stromal gene expression of SDC-1 might be associated with the activation of various growth factors that are related to invasion, progression and metastasis." (PMID 23986011, 2014). "The basic idea is that the shed SDC-1 binds to growth factors derived from the tumor and concentrates them in the tumor microenvironment, promoting their signaling activity." (PMID 24551591, 2014). "This, however, should then warrant further studies on the mechanisms behind the release of syndecan-1 as well as possible predictive effects and effects on epithelial mesenchymal transition in tumours." (PMID 25147801, 2014). "The formation of IGFR/SDC-1/integrin complex seems to be a crucial regulator for integrin-mediated effect in tumor cell metastasis and tumor-induced angiogenesis." (PMID 24551591, 2014). "It has been demonstrated that YKL-40 promotes tumor angiogenesis via initiating a coordination of syndecan-1 and integrin αvβ3 and a following intracellular activation cascade in the membrane of endothelial cells." (PMID 24752554, 2014). "We compared the two different scoring methods based on the locations of SDC1 expression to find the most informative way to evaluate SDC1 expression in tumor cells." (PMID 24373193, 2013). "On the functional level, syndecan-1 affects mesenchymal tumor cell proliferation, adhesion, migration and motility, and the effect varies with the different domains of the core protein." (PMID 24392351, 2013). "The mechanisms of how SDC1 expression is altered in tumor cells and the downstream pathways promoting invasion and metastasis are not clearly understood." (PMID 24373193, 2013). "Therapeutic options should, however, consider that the syndecan-1 expression differs significantly from one tumor type to another and its effect is highly divergent comprising both anti-proliferative and pro-tumorigenic effects." (PMID 24392351, 2013). "One compound that seems to modulate the level of nuclear syndecan-1 in several tumor types is heparanase when simultaneously present in the nucleus." (PMID 24392351, 2013). "Staining of the SCP tumor cells for immunomarkers usually reveals positivity for CD79a, CD138 (syndecan-1, plasma cell specific marker), and epithelial membrane antigen (EMA), as well as negativity for pan-B-cell antigens, CD19, and CD20." (PMID 24260722, 2013). "The detail understanding of altered control mechanisms of proteoglycans, such as SDC1, in tumor cells, will facilitate proteoglycan use in the diagnosis and treatment of cancer patients." (PMID 24373193, 2013). "Syndecan-1 expression was significantly decreased in the cancer epithelial cells but increased in tumour stroma." (PMID 23691363, 2013). "The mechanisms by which syndecan-1 regulates tumor cell behavior are complex, and depend, at least partly, upon the interplay between tumors and the surrounding matrix." (PMID 24392351, 2013). "Recently the number of studies focusing on syndecan-1 in tumours of mesenchymal origin rapidly increases." (PMID 22745764, 2012). "Taken together, this work is the first to present syndecan-1 playing a tumour promoter role in a mesenchymal tumour cell line, a process that progreses through the cooperation of syndecan-1 and syndecan-2." (PMID 22745764, 2012). "In squamous cell carcinoma, the reduction of syndecan-1 expression is correlated with the progression of carcinogenesis, histological grade of malignancy, tumor size and the mode of invasion." (PMID 22905270, 2012). "This is the first report demonstrating that syndecan-1 enhances malignancy of a mesenchymal tumour cell line, via induction of syndecan-2 expression." (PMID 22745764, 2012). "After 1 day, significant differences between the EGFP control and the syndecan-1 transfectant groups were found in the size of primary tumours by t-test (*p<0.05)." (PMID 22745764, 2012).
tumor (continued). "The high levels of heparan sulfate in the tumor microenvironment resulting from syndecan-1 shedding also act as positive regulators that condition the microenvironment for robust tumor growth." (PMID 22649466, 2012). "In a number of neoplasms, expression patterns of syndecan-1 and syndecan-2 characteristically correlate with the tumour stage and grade." (PMID 22745764, 2012). "Taken together, our results show that syndecan-1 decreases migration and motility, and enhances adhesion of mesenchymal tumor cells in an expression level-dependent manner." (PMID 21731601, 2011). "We modulated syndecan-1 expression levels in two mesenchymal tumor cell lines: a human fibrosarcoma B6FS cell line and a human malignant mesothelioma (MM) STAV-AB cell line." (PMID 21731601, 2011). "In a variety of epithelial cancers, SDC-1 expression is reduced or totally lost with tumor progression and aggressive phenotype and low SDC-1 expression was shown to be associated with poor prognostic outcome and shorter survival." (PMID 21655218, 2011). "Our recent publications have demonstrated that syndecan-1 translocates into the nucleus and hampers tumor cell proliferation." (PMID 21731601, 2011). "The biological functions of syndecan-1 potentially affect several steps in tumor progression and facilitate metastasis." (PMID 22214534, 2011). "Both full-length and truncated syndecan-1 constructs decrease tumor cell migration and motility, and affect cell adhesion." (PMID 21731601, 2011). "When we examined the effect of syndecan-1 on the motility/migration of mesenchymal tumor cells using the wound-healing assay, the overexpressing cells showed slower wound closure." (PMID 21731601, 2011). "Our results demonstrate that syndecan-1 regulates mesenchymal tumor cell adhesion and migration, and different domains have differential effects." (PMID 21731601, 2011). "In the light of our recent findings, showing that full-length syndecan-1 and its specific domains inhibit mesenchymal tumor cell proliferation, we investigate, in the present study, its role in cell adhesion and migration." (PMID 21731601, 2011). "In the present study, we further demonstrate that syndecan-1 influences also the adhesion, motility and migration of these two mesenchymal tumor cell lines." (PMID 21731601, 2011). "Transfection of syndecan-1 into mesenchymal tumor cells that express very low levels of endogenous syndecan-1 is a way to influence intrinsic ability." (PMID 21731601, 2011). "We have further shown that SDC-1 plays a key role in the anti-tumor properties of n-3 PUFA through induction of apoptosis via inhibition of the PDK-1-Akt-Bad signaling pathway." (PMID 21655218, 2011). "This complex regulation must also be considered when evaluating effects of syndecan-1 overexpression on tumor cell behavior." (PMID 21731601, 2011). "Overall, these results suggest a model where heparanase upregulation by tumor cells degrades heparan sulfate chains and enhances syndecan-1 shedding." (PMID 20200931, 2010). "The shed and active syndecan-1 is free to diffuse within the tumor microenvironment or to enter the circulation and travel to distal tissues, where it affects the behavior of host cells, such as osteoclasts and their precursors." (PMID 20200931, 2010). "Together these data suggest that syndecan-1 shed by tumor cells exerts biologic effects distal to the primary tumor and that it participates in driving osteoclastogenesis and the resulting bone destruction." (PMID 20200931, 2010). "Decreased expression of syndecan-1 has been previously reported to correlate with increased tumorigenicity and with tumor invasion and progression." (PMID 19865524, 2009). "The enhanced shedding of syndecan-1 is important biologically, because the shed proteoglycan remains active and can influence a wide array of behaviors such as tumor growth and metastasis, chemokine localization, leukocyte trafficking and pathogen virulence." (PMID 19305494, 2009).